SPHK1 (sphingosine kinase 1)
Diseases named in the same sentence as SPHK1 in open-access papers (continued):
Sharing a sentence is not in itself a finding about the gene and the disease.
colon carcinoma (42 papers, 2011 to 2024). "In a SphK1-knockout model, mice showed partial resistance to chemically induced colitis, and in cancer-associated colitis, significant attenuation of colon cancer was achieved." (PMID 35158806, 2022). "In contrast, chronic activation of S1PR1 by S1P, the product of sphingosine kinase 1 (SphK1) in colitis‐associated cancer increases the risk for colon cancer." (PMID 27239439, 2016). "To answer this question, we measured the cellular content of both ceramides and S1P, along with the expression of proteins involved in the proliferation/apoptosis pathways, and assessed the apoptosis rate of colon cancer cells in which the genes encoding SPHK1 and SGPL1 had been silenced." (PMID 37108361, 2023). "Moreover, azoxymethane (AOM)-driven colon cancer in mice increased blood levels of S1P, and SPHK1-deficient mice had reduced colon cancer development." (PMID 35163211, 2022). "Alternatively, overexpression of SphK1 and aberrations in the “inside-out” dual mechanism of SphK1/S1P activation have been reported as contributors to cancer and inflammation, and this is supported by studies in SphK1-deficient mice, for example, reduction of SphK1 reduced colon cancer development." (PMID 28415564, 2017). "Elevated SPHK1 augments colon cancer cell proliferation, and SPHK1 overexpression in intestinal epithelium significantly increases tumor multiplicity." (PMID 37108361, 2023). "Several studies have revealed that the SIP/Sphk1 signaling plays oncogenic roles and it is overexpressed in colon cancer tissue which is correlated with poor survival." (PMID 37448516, 2023). "SphK1, S1P, and S1PRs are gaining increasing importance as generic regulators of inflammatory immune responses and the importance of the role of cellular SphK-S1P-S1PR action in colon cancers has been covered in a couple of recent reviews and book chapters." (PMID 35158806, 2022). "Increased expression of SPHK1 has also been shown to promote colon cancer growth and progression by inducing the expression of MMP-2 and MMP-99,10." (PMID 36309544, 2022). "SPHK1 expression was increased in human colon cancer samples compared to normal colon mucosa, which was further increased in metastatic cancer." (PMID 35163211, 2022). "In human colon cancer progression and metastasis, SphK1 and S1P were shown to have higher expression compared to those without cancer/metastasis." (PMID 35158806, 2022). "In vivo, in a murine colon cancer model, SphK1 and S1P were found to be significantly elevated in the mucosa compared to normal mucosa, with a concomitant increase in S1P levels in mice with colon cancer." (PMID 35158806, 2022). "It is worth mentioning that Sphk1 knockout mice models have offered useful insights on the protective role of SPHK1 depletion in oncogenesis, with colon cancer as the pioneered context model." (PMID 34820423, 2021). "For example, many colon cancers exhibit overexpression of SphK1, and a SphK1 knockout mouse model that was exposed to azoxymethane developed less colon tumors than wild-type mice." (PMID 34069611, 2021). "SphK1 overexpression promoted the proliferation of several types of cancer, including ovarian, breast and colon cancer." (PMID 33931106, 2021). "SphK1 deficiency resulted in reduced proliferation of cells and intensified apoptosis in AOM/DSS-induced colon cancer." (PMID 33920887, 2021). "Recently, SPHK1 expression has been demonstrated to be upregulated in numerous cancers, such as breast cancer, colon cancer, and lung cancer." (PMID 33506044, 2021). "Findings from this study suggest that oxaliplatin resistance in colon cancer cells involves the activation of SphK1/S1P/S1PR2 signaling axis that activates ERK signaling pathway resulting in the induction of CD44 expression." (PMID 32456134, 2020). "Different in vitro studies have also adduced a wealth of evidence to support oncogenic role of SphK1 in colon cancer cells." (PMID 32456134, 2020).
colon carcinoma (continued). "Targeting SphK1 has also shown promising results in increasing the effectiveness of targeted therapies in colon cancer." (PMID 32456134, 2020). "Positive regulation of CD44 expression in ERK-dependent manner was detected in response to both, SphK1 overexpression and exogenous S1P stimulus in oxaliplatin-sensitive colon cancer cells." (PMID 32456134, 2020). "This study indicates that SphK1 contributes to metastatic progression of colon cancer by triggering EMT via up-regulation of MMP2/9 expression accompanied by activation of FAK/AKT signaling pathways." (PMID 32456134, 2020). "SphK1 acts in concert with different molecular mediators to promote colon cancer cell growth and survival." (PMID 32456134, 2020). "SPHK1 is highly overexpressed in human colon tumors, as well as in azoxymethane-induced aberrant crypt foci and colon tumors in rodents, where an increased SPHK1 expression seems to correspond with the progression phase of tumor development." (PMID 31801289, 2019). "Whereas, increased expression of Sphk1 in colon cancer cell line HT-29 cells enhances tumor growth in nude mice." (PMID 28991193, 2017). "We have reported that SphK1 and S1P levels were higher in colon cancer induced by AOM than in normal tissue." (PMID 28583134, 2017). "More studies in rodent models have also demonstrated that Sphk1 is overexpressed in the tumors of the ApcMin/+ mouse model of colon cancers and plays critical roles in intestinal tumorigenesis and progression." (PMID 28991193, 2017). "First, we demonstrated that lack of SphK1 expression significantly inhibited AOM-induced colon tumor development using SphK1 KO mice." (PMID 28583134, 2017). "SphK1 KO mice, compared to wild-type mice, demonstrated a significant inhibition in colon cancer development induced by AOM (58.6% vs. 96.4%, respectively, P < 0.005)." (PMID 28583134, 2017). "In vitro, increased expression of Sphk1 promoted colon cancer cell viability and invasiveness, but suppressed cell apoptosis." (PMID 28991193, 2017). "The expression levels of FAK, p-FAK, ICAM1, and VCAM1 were also upregulated with the overexpression of Sphk1 but downregulated with the reduction of Sphk1 in colon cancer cells." (PMID 28991193, 2017). "Using azoxymethane (AOM, colon carcinogen), we analyzed colon tumor development in SphK1 KO and SphK1 overexpression in intestinal epithelial cells regulated by a tet-on system." (PMID 28583134, 2017). "Then SphK1 overexpression in human colon cancer cells (HT-29) enhanced tumor development in a subcutaneous xenograft model." (PMID 28583134, 2017). "To further support the evidence, we investigated the effects of SphK1 using three separate animal models: SphK1 knockout mice, SphK1 overexpressing transgenic mice, and SphK1 overexpression in human colon cancer xenografts." (PMID 28583134, 2017). "We investigated if SphK1 overexpression supports the subcutaneous growth of a human colon cancer xenograft in mice." (PMID 28583134, 2017). "For example, SPHK1 is overexpressed in colon cancer, and the SPHK1/S1P pathway contributes to colon tumourigenesis." (PMID 27811359, 2016). "Different studies reported that SphK1 is overexpressed in human colon cancer and in a murine model of colon carcinomas, and promotes malignant progression of this disease." (PMID 26580959, 2015). "Our results demonstrate for the first time that luteolin can act as inhibitor of SphK2, the predominant SphK isoform in the used CC cell line, as well as in several colon cancer cell lines, but exerts only a modest, if any, effect on SphK1 activity." (PMID 26580959, 2015). "Recent work in our laboratory revealed a positive correlation between SPHK1 and advanced tumor progression and SPHK1 as a predictor for mortality in colon cancer patients." (PMID 25153718, 2014).
colon carcinoma (continued). "Additionally, they found that SphK1 is overexpressed in human colon tumors, including adenomas and adenocarcinomas, and that SphK1 expression is higher in primary colon cancers with metastases than in those without." (PMID 38002302, 2023). "Targeting SPHK1/S1P to modify the therapeutic strategy of tumor patients is a promising approach to enhance the response to immune checkpoint inhibitors in mouse melanoma, breast, and colon cancer models." (PMID 36823149, 2023). "It seems that SPHK1 regulates tumorigenesis and tumor growth in early colon cancer." (PMID 37108361, 2023). "Furthermore, a better response to anti-PD1 and other immune checkpoint inhibitors as well as reduced tumor growth has been observed in murine models of melanoma, breast, and colon cancer upon SPHK1 silencing." (PMID 36672428, 2023). "In addition to oxaliplatin, SphK1 also mediates the effects of 5-fluorouracil (5-FU) in colon cancer, since SphK1 knockdown or pharmacological inhibition enhanced sensitivity of colon cancer cells to 5-FU." (PMID 32456134, 2020). "Indeed, the role of SphK1 as a positive regulator of EMT in colon cancer was corroborated by other studies as well." (PMID 32456134, 2020). "Immunohistochemistry and Western blot analyses of colon cancer tissues and normal colonic tissues showed higher expression of SphK1, FAK (focal-adhesion kinase) and p-FAK in cancerous tissues, which was in correlation with histological grade, stage and metastasis." (PMID 32456134, 2020). "Overexpression of Spns2 is believed to initiate compensatory mechanism by which colon cancer cells restore S1P levels by upregulating SphK1 and SphK2 and activate ERK and AKT signaling pathways that are by all means important for cell survival and cancer progression." (PMID 32456134, 2020). "Previous studies have demonstrated that high expression of SPHK1 in tumors was associated with poor prognosis of pulmonary, gastric, pancreatic and colonic cancer patients and high expression of phosphorylated SPHK1 could promote cell growth and metastasis." (PMID 31723122, 2019). "Finally, SPHK1 has been reported to promote malignant progression in colon cancer, and high SPHK1 expression seems to correlate with advanced tumor stages." (PMID 31801289, 2019). "In this study, we clearly demonstrate that SphK1 KO mice have a reduction in AOM-induced colon carcinogenesis, including tumorigenicity, multiplicity and tumor burden, while forced expression of SphK1 in intestinal epithelial cells exacerbates AOM-induced colon cancer development." (PMID 28583134, 2017). "Notably, this is the first time in which forced overexpression of SphK1 in intestinal epithelium correlated with accelerated colon cancer development induced by AOM." (PMID 28583134, 2017). "Moreover, we demonstrated that overexpression of SphK1 in intestinal epithelial cells significantly enhanced colon tumor development using double transgenic mice with doxycycline treatment." (PMID 28583134, 2017). "We also showed that SphK1 overexpression enhances tumor growth in human colon cancer xenografts." (PMID 28583134, 2017). "Overexpression of SphK1 in human colon cancer xenografts enhances tumor growth." (PMID 28583134, 2017). "In the context of cancer development, there is some suggestion that SphK1 depletion may have some protective effect against the development of some cancers, for example SphK1−/− mice were less inclined to develop colon cancer." (PMID 28869494, 2017). "Furthermore, SphK1 knockout (KO) mice demonstrated a lower incidence of colon cancer development in an inflammation-related colon carcinogenesis model." (PMID 28583134, 2017).
colon carcinoma (continued). "Furthermore, overexpression of Sphk1 in intestinal epithelial cells via a transgenic strategy significantly enhances azoxymethane (AOM)-induced colon tumor formation in mice." (PMID 28991193, 2017). "The present study shows that the SphK1/S1P pathway plays an important role in colon carcinogenesis and tumor growth, thus inhibition of SphK1 may be an effective strategy for colon cancer chemoprevention." (PMID 28583134, 2017). "Furthermore, overexpression of SphK1 in intestinal epithelial cells significantly enhances AOM-induced colon tumor formation (P < 0.05)." (PMID 28583134, 2017). "SphK1 expression regulates the early stage of colon carcinogenesis and tumor growth, thus inhibition of SphK1 may be an effective strategy for colon cancer chemoprevention." (PMID 28583134, 2017). "Moreover, S1P stimulates growth, invasion and survival of colonic tumor cells, and SphK1 and S1P lyase are up- and down-regulated, leading to S1P accumulation in CRC." (PMID 26580959, 2015). "Additionally, it is found that targeting SphK1/S1P/S1PR1 may be a potential therapeutic option to prevent the development from colitis to colon cancer." (PMID 30186855, 2018). "Furthermore, serum SphK1 levels may hold potential in identifying patients with increased colon tumor burden." (PMID 28583134, 2017). "However, recent reports utilizing models of melanoma and colon cancer demonstrated that expression of SPHK1 and S1P by the tumor stroma might also be important in tumorigenesis." (PMID 26716409, 2016). "SPHK1 targeting augmented the response to ICB in murine models of melanoma, breast, and colon cancer and limited Treg infiltration." (PMID 35163211, 2022). "Various studies showed that SPHK1 promotes MMP2 and MMP9 expression in fibroblast‐like synoviocytes and colon carcinoma RKO cells." (PMID 34262394, 2021). "Down-regulation of SphK1 reduces the expression of COX-2 and the production of PGE2 levels in HT-29 cells belonging to human colon cancer." (PMID 33920887, 2021). "Other mechanisms by which SphK1 induces the production and secretion of MMP-2/9 in colon cancer cells to promote cell proliferation and invasiveness include the activation of ERK1/2 and suppression of p38 MAPK pathways." (PMID 32456134, 2020). "The suppression of CD44 expression was induced by inhibition of either SphK1 activity or by blocking S1PR2 receptor leading to down-regulation of CD44 expression levels and ERK activity in resistant colon cancer cells." (PMID 32456134, 2020). "Increased expression levels of SphK1 and CD44 were observed in oxaliplatin-resistant colon cancer cells in comparison with parental cells." (PMID 32456134, 2020). "Lastly, SphK1 and COX-2 intensity tended to reduce overall survival of late stage colon cancer patients." (PMID 28583134, 2017). "Lastly, we demonstrated that SphK1 and COX-2 intensity tended to reduce overall survival of late stage colon cancer patients." (PMID 28583134, 2017). "Next, we examined the effect of SphK1 and COX-2 expression on pathophysiology and prognosis colon cancer." (PMID 28583134, 2017). "Higher activity of SphK1 and SphK2 in oxaliplatin-resistant colon cancer cell line RKO and knockdown of either SphK1 or SphK2 abrogates RKO cells oxaliplatin resistance." (PMID 21490804, 2011). "Mechanism studies have reported that SPHK1 increases the expression of Slug, vimentin, N-cadherin, and FAK in colon cancer Notably, the active interaction of SPHK1 or S1P with ERK pathway promotes autophagy in colon cancer." (PMID 35965565, 2022). "Interestingly, decreasing SPHK1 expression improves the efficacy of immune checkpoint inhibitors (anti-CTLA-4 and anti-PD-1 therapy) in melanoma, breast, and colon cancer mouse models." (PMID 35565311, 2022).
colon carcinoma (continued). "Previous study showed that SPHK1 may exert metastatic and invasive effects by upregulation of CD44 (hyaluronan receptor) expression through the ERK signaling pathway in colon cancer cells." (PMID 33506044, 2021). "Another study shows that sphingosine, which is phosphorylated by SphK1, resulting in the formation of S1P moiety, via regulating β-catenin levels inhibits the proliferation of cancer cells and induces cell death in SW480 and T84 colon cancer cell lines." (PMID 33920887, 2021). "SPHK1 regulates the PTK2/FAK (protein tyrosine kinase 2) pathway and activates the EGFR (epidermal growth factor receptor) pathway to confer tumour metastasis in colon cancer and oesophageal cancer." (PMID 34857818, 2021). "Study in colon cancer cells has indicated that specific stress stimuli such as serum deprivation increases mRNA, protein and enzyme activity of SphK2 but not SphK1." (PMID 32456134, 2020). "Therefore, we believe SPHK1, TREG, CASP9 and IL4 can be regarded as potential drug targets that are critical for the treatment of colon cancer." (PMID 31138124, 2019). "Studies using genetic knockdown of SphK1 and SphK2 in mouse colon cancer models revealed SphK1−/− mice were significantly protected against colon cancer whereas this protection was not evident in SphK2−/− mouse models." (PMID 28415564, 2017). "Finally, immunohistochemical analyses for SphK1 and COX-2 were performed on human colon cancer tissue microarray." (PMID 28583134, 2017). "SphK1 and COX-2 intensity tended to reduce overall survival of late stage colon cancer patients." (PMID 28583134, 2017). "In addition, in the colon, SphK1 regulates the inflammatory cyclooxygenase-2 (COX-2), and elevated COX-2 is both a biomarker for poor patient outcome and a therapeutic target for colon cancers." (PMID 35158806, 2022). "Consequently, reducing S1P levels by silencing SPHK1 improves the efficacy of anti-CTLA-4 and anti-PD-1 immunotherapy, leading to significant tumor suppression and overall improved survival in mouse melanoma, breast, and colon tumor models." (PMID 35565311, 2022). "This may be explained by divergent functions of SPHK isoforms in inflammation, as has been noted in a model of inflammation-induced colon cancer, where SPHK2 ablation triggered SPHK1-dependent cytokine production in myeloid cells and thus promoted M1 macrophage activation." (PMID 31379883, 2019). "Lastly, SphK1 and COX-2 intensity did not significantly reduce overall survival of late stage colon cancer patients." (PMID 28583134, 2017). "However, no group has previously investigated whether SphK1 enhances colon cancer." (PMID 28583134, 2017). "Results may suggest that both SphK1 and COX-2 play important roles in the early stage, but not the late stage of colon cancer." (PMID 28583134, 2017).